RASSF8 (Ras association domain family member 8)
Diseases named in the same sentence as RASSF8 in open-access papers (continued):
Sharing a sentence is not in itself a finding about the gene and the disease.
tumor (21 papers, 2012 to 2024). "In OC, miR-320a promotes the growth and invasion of tumor cells by targeting Ras association domain family member 8, and the overexpression of miR-320a manifests a worse prognosis and high risk of metastasis." (PMID 38233863, 2024). "Ras association domain-containing protein 8 (RASSF8) is an acknowledged tumor suppressor of lung cancer." (PMID 33710806, 2021). "This suggests that miR-320a plays an oncogenic role in tumour progression via targeting RASSF8, a tumor suppressor gene." (PMID 38690293, 2024). "As a potential tumor suppressor gene, RASSF8 interacts with adherens junction component and adhesion-related β-catenin/E-cadherin to regulate cell adhesion function." (PMID 34341331, 2021). "For example, hypoxia-inducible microRNA-224 promotes the GC cell growth, migration and invasion by directly targeting RASSF8, but miR-34a can act as a tumor suppressor targeting IGF2BP3 in gastric carcinogenesis." (PMID 29296232, 2017). "This study is a first report showing that inhibiting RASSF8 can increase the development of xenograft tumors in vivo, supporting its role as a tumor suppressor gene." (PMID 26334503, 2015). "Several studies indicate that RASSF8 functions as a tumor suppressor in diverse cancers." (PMID 28173803, 2017). "Growth and size of tumor increased when RASSF8 was inhibited by RASSF8 shRNA." (PMID 26334503, 2015). "Moreover, RASSF8 exhibits tumor-suppressive properties and is involved in cell junction maintenance, which may be related to skin sensitivity through altered cell–cell interactions." (PMID 39598151, 2024). "Therefore, RASSF8 may also play similar tumor suppressor function in ccRCC, and the higher level of hsa-mir-29c_59u in ccRCC may lead to the decreased expression of RASSF8 in ccRCC, which consequently promotes the initiation and/or progression of ccRCC." (PMID 37704698, 2023). "The results indicate that miR-320a may accelerate tumor progression by downregulating RASSF8." (PMID 33718138, 2021). "Moreover, lack of RASSF8 expression leads to increased cell migration and tumor aggression." (PMID 34341331, 2021). "These included well-known receptor tyrosine kinase genes (EGFR, TEK and OSMR) that activate MAPK and PI3K signaling pathways, and other tumor-promoter genes (ATP8B2, DAAM1, SLAMF8 and SRGN) as well as tumor-suppressor genes (A2M, DAPK1, RASSF8 and SOCS3)." (PMID 37190308, 2023). "Although there are structural differences between classical and N-RASSFs, RASSF8 and RASSF10 also act as a tumor suppressors while RASSF7 regulates cell growth and apoptosis." (PMID 29108261, 2017). "RASSF8, an N-terminus RASSF, has been shown to be ubiquitously expressed throughout the murine embryo and in normal tissues of human adults, and has been described as a potential tumor suppressor in lung carcinogenesis." (PMID 27626930, 2016). "On the contrary, RASSF8 and RASSF10 have been shown to be reduced in multiple cancers, including lung cancer, gastric cancer, cervical cancer, breast cancer, colorectal esophageal squamous cell carcinoma, and hepatocarcinoma, and thus are considered as tumor suppressors." (PMID 34341331, 2021). "We apply TRUP to RNA-seq data of different tumor types, and find it to be more sensitive than alternative tools in detecting chimeric transcripts, such as secondary rearrangements in EML4-ALK-positive lung tumors, or recurrent inactivating rearrangements affecting RASSF8." (PMID 25650807, 2015).
cancer (7 papers, 2015 to 2024). A tumor composed of atypical neoplastic, often pleomorphic cells that invade other tissues. "Among various predicted cancer-associated genes, we selected RASSF8 as a candidate target for further study." (PMID 27626930, 2016). "There have been comparatively few studies of RASSF3, RASSF4, and RASSF8, though it is clear their expression is downregulated in numerous human cancers." (PMID 39009833, 2024). "We furthermore detected inactivating rearrangements affecting RASSF8, supporting its role as a tumor suppressor gene in cancer." (PMID 25650807, 2015). "RASSF8 was initially cloned and identified by our group as HOJ1 (NCBI Gene ID:11228) on chromosome12p12.3, and shown to be expressed in several cancers." (PMID 26334503, 2015).
RASSF8 also shares sentences with these, for which no sentence is quoted: breast carcinoma (1 paper); gastric tumors (1); liver cancer (1); malignant breast tumors (1).